RNA5S3 (RNA, 5S ribosomal 3)
Synonyms: RN5S3
Gene: Ribosomal RNA gene on chromosome 1 (228,614,750 to 228,614,868, reverse strand). Ensembl gene ENSG00000199337.
Gene Ontology:
Molecular function: structural constituent of ribosome
Cellular component: ribosome
Homologues: Orthologues: macaque 5S_rRNA (100% identical), pig 5S_rRNA (100% identical). Paralogues in human: RNA5S1 (100% identical), RNA5S10 (100% identical), RNA5S11 (100% identical), RNA5S12 (100% identical), RNA5S13 (100% identical), RNA5S14 (100% identical), RNA5S15 (100% identical), RNA5S16 (100% identical), RNA5S17 (100% identical), RNA5S2 (100% identical), RNA5S4 (100% identical), RNA5S5 (100% identical), and 26 more.